TNF (tumor necrosis factor)
Diseases named in the same sentence as TNF in open-access papers (continued):
Sharing a sentence is not in itself a finding about the gene and the disease.
status epilepticus (27 papers, 2011 to 2025). Status epilepticus is defined as a continuous seizure lasting more than 30 min, or two or more seizures without full recovery of consciousness between any of them. "Recently, we demonstrated that microglia‐derived TNF rapidly disrupts interastrocytic GJ coupling during KA‐induced status epilepticus." (PMID 39607395, 2025). "Repeated application of levetiracetam (orally, 360 mg/kg for 2 days) attenuated the expression of interleukin-1β (IL-1β) and TNF-α in the hippocampus of mice after status epilepticus." (PMID 40431461, 2025). "In animal models of kainic acid (KA)-induced status epilepticus (SE), inflammatory cytokines like interleukin-1 beta (IL-1β), interleukin-6 (IL-6), and tumor necrosis factor alpha (TNF-α) were notably increased in microglia following seizures." (PMID 39684432, 2024). "Both microglial pro-inflammatory cytokines (IL-1β and TNF-α) and anti-inflammatory cytokines (IL-4 and IL-10) showed increased expression after pilocarpine-induced status epilepticus, indicating a complex role of microglia in the epileptic brain." (PMID 34924959, 2021). "The expression levels of microglial pro-inflammatory cytokines (TNF-α and IL-1β) and anti-pro-inflammator cytokines (IL-10 and IL-4) increase in brain after status epilepticus." (PMID 34924959, 2021). "Following an insult, such as a seizure or period of status epilepticus, pro-inflammatory cytokines, such as IL-1β, tumor necrosis factor-α (TNF-α) and IL-6 are released in the brain, primarily from astrocytes and microglia." (PMID 29563872, 2018). "Comparisons of TNF-α levels among afebrile and febrile controls, and the four seizure groups showed higher levels in the afebrile status epilepticus attacks in intractable epilepsy patients and the recurrent attack febrile seizure groups (p = 0.06)." (PMID 21989210, 2011). "The mean TNF-α level of afebrile controls was 3.4 pg/mL, while that in febrile controls was 5.6 pg/mL, and that in afebrile status epilepticus attacks in intractable epilepsy patients was 14.2 pg/mL." (PMID 21989210, 2011). "The results show that pharmacological inhibition of necroptosis using Nec-1s, a specific inhibitor of RIPK1, or selective inhibition of soluble TNFα by XPro1595, as well as genetic knockout of TNFR1, effectively rescued CA1 astrocyte loss caused by kainate-induced status epilepticus." (PMID 40629542, 2025). "An unexpected finding in the present study was that knock-out of the P2X7R was associated with higher release of cytokines post-status epilepticus, including both pro- and anti-inflammatory cytokines (e.g., IL-10, IL-12p70, IL-27/30, IL-4, KC/GRO MIP-1α, MIP-2, TNF-α)." (PMID 34572093, 2021). "Inhibiting this receptor during status epilepticus reduced tumor necrosis factor alpha (TNF-α), a major inflammatory cytokine, which, along with interleukin 1 beta (IL-1β), initiates the immune response in the CNS, leading to neuronal damage and hyperexcitability." (PMID 31935804, 2020). "H19 overexpression induced the activation of astrocytes and microglia and the release of proinflammatory cytokines (interleukin-1β and interleukin-6 and tumor necrosis factor-α) in the hippocampus, whereas H19 knockdown inhibited status epilepticus-induced glial cell activation." (PMID 29636074, 2018). "In the present study, we addressed the question of whether P2X7 receptor-mediated TNF-α regulation is involved in pathogenesis and outcome of status epilepticus (SE)." (PMID 21631954, 2011). "In an animal model, pretreatment of silibinin (50, 100, and 200 mg/kg) in kainic acid (KA) - induced status epilepticus (SE) in mice showed a significant neuroprotective effect that might be due to reducing the expression of inflammatory cytokines IL-1β and TNF-α." (PMID 38106632, 2023). "Interestingly, inhibition of TNFα by soluble TNF p55 receptor attenuates status epilepticus-induced oedema in a rat model, which could be relevant in CM, as seizures are highly prevalent." (PMID 26691993, 2015).
status epilepticus (continued). "A study examining patients with autoimmune epilepsy presenting with new-onset refractory status epilepticus found elevated levels of IL-6, TNF-α, IL-2, and IL-4 in the CSF, and elevated levels of IL-6 and TNF-α in the periphery." (PMID 31552027, 2019). "Pre-treatment with Tualang honey reduced neuroinflammation by reducing the elevation of TNF-α, IL-1β, glial fibrillary acidic protein, allograft inflammatory factor 1 and COX-2 in the cerebral cortex, cerebellum and brainstem of kainic acid-induced status epilepticus rat." (PMID 33435215, 2021).
African trypanosomiasis (26 papers, 2009 to 2025). "Increased TNF levels have been associated with neuropathology in animal models of sleeping sickness, a human disease induced by infection with the extracellular parasite Trypanosoma brucei, and malaria, caused by Plasmodium sp." (PMID 28877735, 2017). "In addition to direct killing of parasites, BMAP-18 was shown to inhibit LPS-induced secretion of tumour necrosis factor alpha (TNF-α), a cytokine that is associated with inflammation and cachexia (wasting) in sleeping sickness patients." (PMID 19190729, 2009). "In the LQ group, several signaling pathways were significantly enriched, including “African trypanosomiasis,” “TNF signaling pathway,” and “IL‐17 signaling pathway”." (PMID 41306337, 2025). "In mouse models of human African trypanosomiasis, proinflammatory mediators like the tumor necrosis factor (TNF-α), interferon-gamma (IFN-γ), and CXC ligand 10 (CXCL10) have been crucial to parasite CNS invasion." (PMID 34158806, 2021). "DEGs were mainly enriched in cytokine receptor interaction, TNF signaling pathway, and African trypanosomiasis." (PMID 33551833, 2020). "In this regard, recent work demonstrates that TNF-α and iNOS producing dendritic cells (Tip-DCs) also play a deleterious role during African trypanosomiasis." (PMID 28936213, 2017). "In ECM and African trypanosomiasis TNF has been shown to be crucial for parasite control, but has also been associated with the severity of neurological symptoms in the human disease." (PMID 26915097, 2016). "Similarly, a possible pathogenic mechanism of sleep disturbances observed in human African trypanosomiasis (HAT) patients is the upregulations of cytokines such as interleukin-1 beta (IL-1β) and tumor necrosis factor-alpha (TNF-α)." (PMID 35095888, 2021). "1.Therapeutic Targeting of CXCL10 and TNF-α: Since CXCL10 and TNF-α play significant roles in promoting neuroinflammation and disease progression, targeted therapies aimed at modulating these cytokines may improve outcomes in African trypanosomiasis." (PMID 40977748, 2025).
human papillomavirus infection (26 papers, 2018 to 2026). "Pathways in which the KEGG pathway was highly enriched in circRNA included the cell cycle, human papillomavirus infection, TNF signaling pathway, thyroid hormone signaling pathway, and FOXO signaling pathway." (PMID 40951426, 2025). "The hubs and bottlenecks regulate functional pathways, including MAPK signaling pathway, human cytomegalovirus infection, neurotrophin signaling pathway, shigellosis, human papillomavirus infection, IL-17, and TNF signaling pathways." (PMID 38224029, 2023). "Genes in the E. coli F18a and L. reuteri coincubation group compared with the E. coli F18a group were most substantially enriched in the tumor necrosis factor production and the Human papillomavirus infection." (PMID 36876070, 2023). "The MAPK, neurotrophin, and TNF signaling pathways, IL-17, and human cytomegalovirus infection, human papillomavirus infection, and shigellosis were identified as significant pathways involved in graft rejection." (PMID 38224029, 2023). "Compared with cluster 5, the results showed that cluster 1 was mainly enriched in the FoxO signaling pathway, human papillomavirus infection, TNF, and IL-17 signaling pathway." (PMID 36064702, 2022). "Specifically, in UM, TFPI2 coexpression genes are mainly associated with pathways of human papillomavirus infection and calcium signaling, while in CM, TFPI2 coexpression genes are mainly associated with cytokine–cytokine receptor interaction and TNF signaling pathways." (PMID 34249699, 2021). "These DEPs are mainly enriched in human papillomavirus infection, PI3K-Akt signaling pathway, coronavirus disease, IL-17 signaling pathway and TNF signaling pathway through KEGG analysis." (PMID 36709303, 2023). "In addition, we observed enriched immune response related terms such as cGMP-PKG signaling pathway, TNF signaling pathway and IL-17 signaling pathway, as well as human papillomavirus infection in SIRT7-KO cells with or without GPS infection." (PMID 40636259, 2025).
Hyperammonemia (26 papers, 2014 to 2026). An increased concentration of ammonia in the blood. "ALF is known to be frequently associated with systemic inflammation and, in addition to hyperammonemia, increased LPS and tumor necrosis factor-alpha (TNF-α) levels together induce AHE." (PMID 36430933, 2022). "We assessed whether the induction of TNF-a by hyperammonemia is associated with increased nuclear expression of NF-κB and how hyperammonemia activates NF-κB." (PMID 32087723, 2020). "In addition, we have demonstrated that the ameliorated blood ammonia levels was associated with decreased circulating levels of TNF-α in NH4Cl-induced hyperammonemia in rats." (PMID 28744340, 2017). "Consequently, TNFα-deficient animals exhibited hyperammonemia." (PMID 28801579, 2017). "Hyperammonemia increases TNFα levels in monocytes, which increases cAMP and PKA activity and reduces LC3 content." (PMID 41601700, 2026). "In, the in vivo treatment with infliximab, an anti–TNFα antibody, prevented microglial and astrocyte activation in the hippocampus induced by hyperammonemia." (PMID 41601700, 2026). "Extracellular vesicles from the plasma of rats with chronic HE and hyperammonemia elevate TNF‐α and its receptor TNFR1 in cerebellar slices from control rats, resulting in increased activation of TNFR1." (PMID 41141377, 2025). "GABA‐ergic tone in the motor cortex was also found to be increased in minimal HE (Grades 1 and 2), and the GABAA antagonist bicuculline decreases IL‐6 and TNFα and increases IL‐10 in the plasma of chronic hyperammonemia rats." (PMID 41141377, 2025). "Hyperammonemia increases TNFα and the number of TNFR1 receptors in the membrane, resulting in an increase in the activation of the TNFR1 receptor, which results in increased translocation of the transcription factor NF-κB to the nucleus." (PMID 41304999, 2025). "Hyperammonemia increases the content of TNFα and the membrane expression of its receptor TNFR1, resulting in increased glutaminase content." (PMID 41304999, 2025). "Rats with chronic hyperammonemia exhibited increased TNFα and TGFβ plasma levels and reduced anti-inflammatory IL-10 levels." (PMID 41304999, 2025). "Purkinje neurons, located in the cerebellum, are highly GABAergic, involved in motor projections, and have been shown to secrete increased TNF‐α via nuclear factor‐kappa B (NF‐κB) activation during sustained hyperammonemia." (PMID 41141377, 2025). "To advance in the understanding of the cell types involved in triggering this pathway we analyzed in which cell types is the content of TNFα increased by hyperammonemia and reduced by anti-IL-17." (PMID 38671534, 2024). "An enhanced activation of the TNFα-glutaminase-GAT3 pathway mediates a neuroinflammation-induced increase of GABAergic neurotransmission in hyperammonemia." (PMID 39242290, 2024). "For example, hyperammonemia induces neuroinflammation in hippocampus, with activation of microglia and astrocytes and increased pro-inflammatory factors such as IL-1β and TNFα." (PMID 36593485, 2023). "Hyperammonemia increases (p < 0.01) the content of TNFα to 470 ± 38 pg/mg protein compared to 273 ± 28 pg/mg protein in control rats." (PMID 36593485, 2023). "We have identified here some key mechanisms by which enhanced TNFα levels in EVs in hyperammonemia induce neuroinflammation and enhance GABAergic neurotransmission in cerebellum, which would lead to motor incoordination." (PMID 35911759, 2022). "We then analyzed the effects of hyperammonemia and infliximab treatment on the expression of TNF-a in the white matter by immunohistochemistry." (PMID 32087723, 2020). "Increased membrane expression of TNFR1 in rats with chronic hyperammonemia leads to increased nuclear translocation of p50 subunit of NF-κB and, as a consequence, an increase of TNFα, IL1β, and glutaminase expression." (PMID 32917219, 2020).
Hyperammonemia (continued). "We have recently shown using the same animal model used here that hyperammonemia per se induces peripheral inflammation by increasing proinflammatory TNF-a, IL-6, and PGE2 and decreasing anti-inflammatory IL-10." (PMID 32087723, 2020). "Unexpectedly, we also observed an increase in TNF-a expression in Purkinje neurons in rats after 4 weeks of hyperammonemia." (PMID 32087723, 2020). "All these effects of hyperammonemia on brain are prevented by inhibiting the induction of peripheral inflammation with anti-TNFα." (PMID 32121257, 2020). "We analyzed the level of TNF-a mRNA and NF-κB in microglia, astrocytes, and Purkinje neurons in the cerebellum after 1, 2, and 4 weeks of hyperammonemia." (PMID 32087723, 2020). "We show here that sustained hyperammonemia and peripheral inflammation induce TNF-a expression in Purkinje neurons in rats and in patients who die with chronic liver cirrhosis and hyperammonemia." (PMID 32087723, 2020). "Hyperammonemia increased the content of TNFα to 156 ± 8% (p < 0.01) and of IL1β to 132 ± 6% (p < 0.05) of control rats." (PMID 32917219, 2020). "It is therefore likely that hyperammonemia-induced peripheral inflammation is the trigger of TNF-a induction in the cerebellum of rats." (PMID 32087723, 2020). "Over the course of the study, we found that sustained hyperammonemia induced the expression of TNF-a in Purkinje neurons." (PMID 32087723, 2020). "We also used R7050 to assess the role of TNFR1 activation in the induction of NF-κB p50 nuclear translocation and TNF-a expression after 2 weeks of hyperammonemia." (PMID 32087723, 2020). "Here we show that hepatic clearance of NH4+ is impaired in TNFα deficient as well as TNFR1&TNFR2 double knockout mice, which both develop hyperammonemia." (PMID 28801579, 2017). "A role of TNFα during ammonia toxicity has been suggested, but a detailed understanding of its effects during hyperammonemia remained elusive." (PMID 28801579, 2017). "Here, C. molmol resin extract significantly decreased serum levels of TNF-α, demonstrating that its anti-inflammatory effect plays a role in attenuating hyperammonemia." (PMID 28744340, 2017). "The aims were 1) to identify which cell type produces the pathological EV in hyperammonemic rats; 2) to identify the mechanisms by which hyperammonemia increases EV release from monocytes and induces the formation of pathological EV; and 3) to analyze the role of TNFα and PKA in these mechanisms." (PMID 41601700, 2026). "EV from control monocytes treated with TNFα (C-M-EV+TNFα) also induced some of the effects induced by hyperammonemia on these pathways, except for the increase of TNFα in microglia and in the whole hippocampus and the increases in TNFR1, IL-1 receptor, and CCL2." (PMID 41601700, 2026). "Importantly, TNFR1 activation by TNFα contained in these EVs represents a critical upstream step in hyperammonemia-induced glial activation." (PMID 41601700, 2026). "One study found that only patients with systemic inflammation signs of systemic inflammatory response syndrome, and/or elevated levels of proinflammatory cytokines (tumor necrosis factor-a [TNF-a], interleukin-6 [IL-6]) developed HE in the presence of hyperammonemia." (PMID 37892060, 2023). "Hyperammonemia was similar before and after resolution of inflammation in patients.There was a significant decrease in the white blood cell count, nitrate/nitrite, IL-6, IL-1β, and TNF-α by infection treatment.Induced hyperammonemia significantly worsened neuropsychological test scores." (PMID 34361075, 2021). "In addition, chronic hyperammonemia also induces peripheral inflammation, increasing TNFα and decreasing IL-10 levels in the plasma." (PMID 34202516, 2021). "Bicuculline administration reduced TNFα levels after three or five weeks of the hyperammonemic diet but not after only three days of bicuculline treatment (11 days of hyperammonemia), suggesting an effect of the chronic administration of bicuculline rather than an acute effect." (PMID 34202516, 2021).